LAIR1 (leukocyte associated immunoglobulin like receptor 1)
Diseases named in the same sentence as LAIR1 in open-access papers (continued):
Sharing a sentence is not in itself a finding about the gene and the disease.
malaria (9 papers, 2015 to 2025). Malaria is a serious and sometimes fatal disease caused by a parasite that commonly infects a certain type of mosquito which feeds on humans. "Interestingly, in a cohort of malaria-exposed African individuals, antibodies containing LAIR1 inserts with somatic mutations have been identified." (PMID 40563506, 2025). "RIFIN, a large family of Plasmodium variant surface antigens, plays a crucial role in malaria pathogenesis by mediating immune suppression through activation of inhibitory receptors such as LAIR1, and antibodies with LAIR1 inserts have been identified that bind infected erythrocytes through RIFIN." (PMID 34244481, 2021). "The presence of LAIR1/LILRB1-containing antibodies offers new insights into malaria parasite evasion strategies and the immune system’s response." (PMID 38933531, 2024). "Statement of Significance: Uncovering antibodies with LAIR1/LILRB1 domains provides new insights into malaria immunity, opens up avenues for antibody diversification, and proposes novel approaches to antibody engineering." (PMID 38933531, 2024). "The presence of LAIR1/LILRB1 in public antibodies opens new perspectives on how the malignant malaria parasite manipulates host’s immune cell functions." (PMID 38933531, 2024). "These LAIR1 antibodies were found in 5–10% of malaria-experienced individuals, whereas only 0.3% of European donors had LAIR1-containing IgG." (PMID 33193447, 2020). "The recent identification of a novel class of antibody in humans from malaria endemic regions of Africa was therefore surprising as one hypervariable loop contains the entire collagen-binding domain of human LAIR1." (PMID 28527239, 2017). "Interestingly, malaria parasites tend to favor B cells with LAIR1 insertions in the VDJ region over the switch region." (PMID 38933531, 2024). "Antibodies containing LAIR1 and LILRB1 inserts represent a class of naturally occurring antibodies in humans, characterized by their broad-spectrum binding to the malignant malaria parasite’s RIFIN proteins." (PMID 38933531, 2024). "In malaria-prone regions, antibodies containing LILRB1, similar to those with LAIR1, have been identified in patients." (PMID 38933531, 2024). "Receptor-containing antibodies with a portion of the LAIR1 and LILRB1 exons were produced in malaria patients in malaria-endemic areas." (PMID 35784341, 2022). "Moreover, in order to go further in the deciphering of the LAIR-1 and C1q interaction, we studied the implication of residues that were described as important for the interaction with collagen in a family of broadly reactive antibodies against malaria antigens containing LAIR-1 Ig-like domain." (PMID 34066122, 2021). "Moreover, people living in malaria-endemic areas across Africa have unique antibodies, containing exons of LILRB1 and LAIR1, which can bind multiple RIFINs4,6,7." (PMID 40500441, 2025). "Specifically, LAIR1 inserts, absent in those not exposed to malaria, become significant in roughly 5% of malaria-exposed individuals, hinting at the role of inserts in the antibody response." (PMID 38933531, 2024). "However, the presence of LAIR1 antibodies did not correlate with protection against malaria." (PMID 33193447, 2020).
cervical cancer (8 papers, 2020 to 2025). A primary or metastatic malignant neoplasm involving the cervix. "Conversely, LAIR-1 expression suppressed the proliferative ability of human cervical cancer cells and induced apoptosis." (PMID 40806280, 2025). "In the cervical cancer cell line ME-180, the overexpression of LAIR1 was described to inhibit their proliferation and to reverse their anti-apoptosis tendency." (PMID 36555775, 2022).
hepatocellular carcinoma (8 papers, 2020 to 2025). A malignant tumor that arises from hepatocytes. "In hepatocellular carcinoma, a high level of expression of LAIR1 in cancer tissue was associated with poor cancer differentiation and with worse overall survival." (PMID 36555775, 2022). "The high expression of LAIR-1 in hepatocellular carcinoma (HCC) and oral squamous cell carcinoma (OSCC) is correlated with poor differentiation and the presence of an immunosuppressive environment, suggesting its involvement in immune evasion." (PMID 38332915, 2023). "Relevant studies have shown that LAIR-1 can mediate immune escape in oral squamous cell carcinoma and hepatocellular carcinoma." (PMID 35413989, 2022). "This study indicated that LAIR‐1 expression was detected in normal hepatocytes and hepatoma cells." (PMID 37647449, 2023). "This study first indicated that LAIR‐1 overexpression was detected in hepatocellular carcinoma (HCC) cells, and the downregulation of LAIR‐1 levels increased HCC cell viability, colony formation, and invasion, which might be associated with the PI3K‐AKT‐mTOR signaling pathway suppression." (PMID 37647449, 2023).
leukemia (8 papers, 2018 to 2025). A malignant (clonal) hematologic disorder, involving hematopoietic stem cells and characterized by the presence of primitive or atypical myeloid or lymphoid cells in the bone marrow and the blood. "A later study found that LAIR-1 has been linked to cell stemness and disease development in leukemia." (PMID 37966113, 2023). "Overall, these collective results indicate that heightened LAIR-1 signaling via NC525 disrupts receptor pathways that are critical to leukemia cell survival and triggers suppressive pathways that lead to apoptosis and leukemic cell death." (PMID 37966113, 2023). "One study showed that LAIR-1 ligation on leukemia cells inhibited IκBα activation to prevent nuclear factor-κB (NF-κB) translocation into the nucleus, resulting in programmed cell death." (PMID 37966113, 2023). "LAIR-1 can inhibit GM-CSF-dependent proliferation in primary leukemia, prevent proliferation and induce apoptosis in human myeloid leukemia cell lines." (PMID 29915163, 2018). "Expression of LAIR-1 is significantly decreased in the circulating CD4+ T cells in patients with rheumatoid arthritis or leukemia." (PMID 29915163, 2018). "In addition, the in vivo bone marrow engraftment of MV4-11 leukemia cells in transplanted NOD/SCID-IL2RG (NSG) mice was partly impaired using silenced LAIR1 cells, further supporting the need for LAIR1 in optimal leukemia cell growth." (PMID 40563506, 2025). "The knockdown of LAIR1 in human leukemia cell lines resulted in an increase in apoptosis and in the suppression of in vitro cellular growth, indicating that LAIR1 could be essential to support AML development." (PMID 36555775, 2022). "Early studies reported a leukemia-suppressing effect of LAIR-1 on AML cells, where LAIR-1 signaling induced apoptosis and reduced proliferation via SHP-1 and inhibition of NFκB translocation into the nucleus." (PMID 40175626, 2025). "The ablation of LAIR1 surface expression resulted in the hyperactivation of Syk, SRC kinase, and Erk leading to cell death in vitro, remission of leukemia growth in vivo, and prolonged survival in transplant recipient mice." (PMID 40563506, 2025). "While LAIR-1 was dispensable for normal hematopoiesis, knockdown of LAIR-1 in human leukemia cells increased apoptosis in vitro and reduced AML development in murine models." (PMID 37966113, 2023). "As a result, inhibition of expression of the immunoreceptor tyrosine-based inhibition motif (ITIM)-containing receptor LAIR1 does not affect normal hematopoiesis but abolishes leukemia development." (PMID 31013791, 2019). "Mice that received BM from isotype control–treated donors developed AML, while those that received BM from NC525-treated animals showed no propagation of leukemia, indicating that LAIR-1 engagement by NC525 eradicated LSCs within the BM of the PDX donor animals." (PMID 37966113, 2023).
Arthritis (7 papers, 2020 to 2025). Inflammation of a joint. "Mice rendered deficient for LAIR1 show more severe arthritis than their wildtype counterparts." (PMID 36555775, 2022). "Vitamin D suppressed arthritis in LAIR-1-sufficient DR1 mice, while it was ineffective in LAIR-1-/- deficient mice." (PMID 40429939, 2025). "It has been demonstrated that the LAIR1 KO collagen-induced arthritis model develops severe arthritis and has a more significant percentage of affected limbs than wild-type mice." (PMID 39940787, 2025). "LAIR-1 engagement by collagen or the complement component C1q induces inhibitory T cell signalling, and in collagen-induced arthritis, administration of anti-LAIR-1 antibodies significantly attenuated disease." (PMID 38077329, 2023). "Taken together, these data demonstrate that LAIR-1 is critical for the suppression of arthritis induced by systemic administration of collagen." (PMID 36077232, 2022). "When mice were observed for the development of arthritis, the LAIR-1+/+ mice receiving the CI had significantly less severe arthritis compared to littermate controls administered PBS." (PMID 36077232, 2022). "Groups of mice were immunized with CII/CFA to induce arthritis, then were given interperitoneally either polyclonal anti-LAIR-1 antibodies or rabbit IgG." (PMID 34948139, 2021). "When mice were scored for severity of arthritis, as hypothesized, mice treated with α-LAIR-1 antibodies had significantly less severe arthritis than mice given the control IgG." (PMID 34948139, 2021). "Polyclonal antibodies which activate LAIR-1 were also capable of attenuating arthritis." (PMID 34948139, 2021). "Moreover, oral therapy with active forms of vitamin D suppressed arthritis in LAIR-1 sufficient DR1 mice, but were ineffective in LAIR-1−/− deficient mice." (PMID 34948139, 2021). "Engineering LAIR1-LP functionalized hydrogels could be particularly useful in treating inflammatory diseases, such as arthritis." (PMID 32719788, 2020). "Interestingly, it was recently observed that the effect of the vitamin D could be at least partially mediated by the upregulation of LAIR1 in a model of arthritis." (PMID 36555775, 2022). "Since polyclonal anti-LAIR-1 antibodies predominately activate LAIR-1, we used the collagen-induced arthritis model to induce in vivo activation of LAIR-1 and examined the resulting autoimmune arthritis." (PMID 34948139, 2021).
Sepsis (7 papers, 2020 to 2025). Sepsis is defined as life-threatening organ dysfunction caused by a dysregulated host response to infection. "This would be consistent with the elevated expression of the validated endo-lysosomal DEGs GUSB and HEXA (azurophilic granules) as well as LAIR1 (specific granules) in high-density blood neutrophils from ICU patients with sepsis." (PMID 35844509, 2022). "LAIR1 expression was higher in patient monocytes during sepsis compared to HC and was restored to HC levels after the recovery process." (PMID 32973751, 2020). "Human sepsis is an example of a dysregulated inflammatory response to infection and represents an interesting model to comprehend LAIR-1 dynamics in vivo." (PMID 32973751, 2020). "In the high-risk group, LAIR1 was also elevated, as were immunosuppressive genes CD276, ICOSLG, and PDCD1LG2, which is consistent with immunosuppressive status in sepsis patients and further indicates that poor prognosis in patients with sepsis may be closely linked to immunosuppression." (PMID 40504881, 2025). "Mechanistically, we demonstrate that MMP9 suppresses NFAT activation by impairing TCR signaling via Lair-1-mediated ZAP70 inhibition and by disrupting CRAC-channel-dependent calcium influx—interactions previously unrecognized in the context of sepsis." (PMID 41306770, 2025). "In contrast to MERTK, which was regulated similarly in the two mouse strains, LAIR-1 expression was differentially regulated in C57BL/6J and BALB/c in the context of sepsis, with LAIR-1 expression significantly upregulated only in CLP C57BL/6 CD11b+Ly6Chigh monocytes." (PMID 39506629, 2024). "Any of the three and/or the pooled sepsis groups significantly differed from the ICU controls for a total of eleven genes, including higher sepsis levels for the endo-lysosomal genes DIAPH2, GUSB, HEXA, LAIR1, and SGSH." (PMID 35844509, 2022).
chronic lymphocytic leukemia (6 papers, 2012 to 2025). "LAIR-1 expression in chronic lymphocytic leukemia (CLL) is associated with disease stage and the proliferation of malignant hematopoietic cells." (PMID 33396670, 2020). "We have recently reported that LAIR1 is downregulated in B cells of chronic lymphocytic leukaemia (CLL)." (PMID 22355402, 2012). "Similarly, LAIR1 is expressed on B cells of chronic lymphocytic leukemia (CLL)." (PMID 40563506, 2025). "Additionally, LAIR-1 is absent in high–risk B cell chronic lymphocytic leukemia cells and LAIR-1 is downregulated on NK cells isolated from patients enduring a chronic active Epstein-Barr virus infection." (PMID 32973751, 2020). "Additionally, LAIR-1 expression varies in chronic lymphocytic leukemia (CLL); it is absent in high-risk CLL, differently expressed in intermediate- and low-risk CLL, and significantly lower in CLL patients compared to healthy donors, correlating with disease stage and progression." (PMID 40806280, 2025).
Cirrhosis (6 papers, 2019 to 2025). A chronic disorder of the liver in which liver tissue becomes scarred and is partially replaced by regenerative nodules and fibrotic tissue resulting in loss of liver function. "Thus, monocyte LAIR1 expression has been proposed as a novel biomarker for the early detection of liver damage caused by cirrhosis." (PMID 40563506, 2025). "Sept1 maintains Golgi integrity in hepatocytes, supporting liver development 70, while elevated expression of Lair1 on circulating monocytes marks early cirrhosis." (PMID 40791429, 2025). "This is likely due to the higher levels of collagen present during cirrhosis and competition between the anti-LAIR1 antibody and the LAIR1 natural ligand." (PMID 40563506, 2025). "The differences in blood monocyte LAIR-1 expression between cirrhotic patients and healthy controls were evident even at early stages of cirrhosis progression." (PMID 31019980, 2019). "Therefore, we were unable to observe changes in LAIR-1 expression in the sustained progression of “CHB–cirrhosis–HCC,” although it is of keen interest." (PMID 34398030, 2021). "However, the amount of LAIR-1 expressed per cell (MFI) was statistically higher in blood monocytes from patients with cirrhosis compared to healthy donors (P = 0.0011)." (PMID 31019980, 2019). "Differences in expression of LAIR-1 in human tissue macrophages between cirrhosis and RA, both chronic systemic inflammatory diseases, could be caused by their opposite effects on tissue collagen, the known ligand for LAIR-1 receptor, among others." (PMID 31019980, 2019). "In the current study, we aimed to examine whether LAIR-1 influences HCC susceptibility by performing a case-controlled study in a population of Egyptian patients, evaluating the association between HCV G4 post-treatment and liver cirrhosis risk or cirrhosis progression to HCC." (PMID 36293412, 2022).
glioblastoma (6 papers, 2021 to 2025). The most malignant astrocytic tumor (WHO grade IV). "The authors’ interest in LAIR1 was inspired by the discovery of high LAIR1 expression in macrophages and microglia within human glioblastoma multiforme (GBM) tumors and M2-like TAMs in murine GBM models." (PMID 40829176, 2025). "The analysis revealed that LAIR‐1 was a risk factor for LGG, glioblastoma (GBM), kidney renal clear cell carcinoma (KIRC), thymoma (THYM), skin Cutaneous Melanoma (SKCM), and uveal Melanoma (UVM)." (PMID 35702880, 2023). "The expression of LAIR1 in low-grade glioma (LGG) and glioblastoma (GBM) tissues was notably higher compared to its healthy counterpart." (PMID 40563506, 2025).
melanoma (6 papers, 2020 to 2024). A malignant, usually aggressive tumor composed of atypical, neoplastic melanocytes. "To determine the effect of genetic ablation of LAIR-1 on tumour outgrowth in vivo, we injected Lair1+/+ and Lair1−/− mice subcutaneously (s.c.)with the B16-F10 melanoma cancer cell line in Matrigel and determined tumour size over time." (PMID 38236251, 2024). "LAIR1 expression has been reported to be prognostic of improved clinical outcomes in patients with advanced melanoma and with macrophage content in the TME." (PMID 37435077, 2023). "Lastly, the analysis of melanoma patients treated with PD-1 blockade reveals that increasing gene expression of collagen, LAIR1, or TIM-3 predicts poorer overall survival or therapeutic response to immune checkpoint blockade." (PMID 32908154, 2020). "In melanoma, LAIR1 deletion promotes its metastatic growth, LAIR1 expression is associated with improved clinical outcomes in human metastatic melanomas, and LAIR-1 may be a promising cancer therapeutic target." (PMID 38690275, 2024). "Clinically, increased collagen, LAIR1, and TIM-3 expression in melanoma patients treated with PD-1 blockade predict poorer survival and response." (PMID 32908154, 2020).